S100A4 (S100 calcium binding protein A4)
Diseases named in the same sentence as S100A4 in open-access papers (continued):
Sharing a sentence is not in itself a finding about the gene and the disease.
tumor (continued). "In the same direction, strategies designed to block any step in the signaling induced by S100A4 in tumor vasculature might represent potential approaches to tackle tumor growth and dissemination, and hence a contribution to the development of novel antitumoral and/or antiangiogenic therapies." (PMID 24023743, 2013). "We further sought to determine whether S100A4 has a critical role in some animal tumor models." (PMID 24023743, 2013). "EMT-related proteins such as E-cadherin, β-catenin, and S100A4 are known to be related to carcinogenesis and tumor progression, but the relation of these protein expressions and whether these proteins can serve as prognostic biomarkers of CRC were not clarified." (PMID 23783026, 2013). "Furthermore, certain lines of evidence suggest that S100A4 may have tumor suppressor functions in the lung." (PMID 22853000, 2012). "However, upon transfection of an expression vector for AGR2 into parental Rama 37 cells and their transplantation into syngeneic rats, the primary tumours appear on average with an increased latency compared to that for S100A4-transfected, osteopontin-transfected or the parental Rama 37 cells." (PMID 16598187, 2006). "S100A4 may be released from both tumour and/or stroma cells by an as yet undetermined mechanism." (PMID 15900299, 2005). "S100A4 can also be secreted and once extracellular can affect several facets of tumour progression such as angiogenesis, stimulation of cell motility, upregulation of matrix metalloproteinases (MMPs), modulation of tumour-related transcription factors, and potentially as a stromal factor." (PMID 15900299, 2005). "However the actual mechanism of tumour-promoting function of S100A4 remains to be determined." (PMID 15900299, 2005). "Furthermore, when the level of S100A4 protein in the cultured cells was plotted against the percentage of tumour-bearing mice with lung metastases, a straight line could be drawn through the three points (least-squares regression analysis R2=0.9965; P=0.038)." (PMID 14710237, 2004). "In order to find out whether a particular subtype of lymphocytes contained the S100A4, serial sections of some tumour specimens were immunocytochemically stained with antibodies to S100A4, and also with antibodies to CD3 and CD79a antigens for T and B lymphocytes, respectively." (PMID 11875708, 2002). "The transcription of S100A4 has high relevancy in promoting the execution of CRC metastasis through intracellular and extracellular mechanisms, as well as to modulate the tumor microenvironment to a pro-metastatic state 19-20." (PMID 40765817, 2025). "(K) Western blotting of macrophage pro-tumor indicators (VEGF, MMP9, TGF-β, and HIF-1α) in S100a4-OE MH-S." (PMID 40658605, 2025). "Our findings reveal that hsa-miR-125b-5p is downregulated upon activation of RAGE by its ligand s100a4, leading to increased MMP-2 expression and enhanced tumor invasion potential." (PMID 41155277, 2025). "High expression of S100A4 facilitates NSCLC metastasis and immunosuppression via exosomes and the STAT3 pathway, which results in poor tumor differentiation, inhibition of autophagy, and worse prognosis." (PMID 41164170, 2025). "Immunohistochemical results were consistent with in vitro, and elevated RP11-54O7.17 significantly reduced the protein content of S100A4, p-STAT3 and Ki-67 in tumor tissues and suppressed the expression of p-STAT3 and S100A4." (PMID 41173847, 2025). "It has been reported that CD36 is the main effector of the S100A4/PPAR-γ pathway, and its mediated fatty acid uptake plays an important role in the tumor-promoting function of macrophages." (PMID 40658605, 2025). "In total, 469 genes exhibited higher expression levels in tumor tissues compared to normal tissues, including S100A6 and S100A4." (PMID 40723292, 2025). "Mechanistically, S100A4 promotes EMT and interacts with matrix metalloproteinases (MMPs), facilitating ECM degradation and enabling tumor cell dissemination." (PMID 41404073, 2025).
tumor (continued). "The expression of S100A4 was significantly elevated in GBM tissues compared to normal brain (p < 0.05), consistent with its established roles in tumor progression, stemness, and resistance to therapy." (PMID 41002392, 2025). "Key proteins identified, including ANXA1, SLC2A1, S100A4, and NFKB1, contribute to tumour progression and the resistance phenotype." (PMID 40004024, 2025). "In summary, S100A4 is a promising target in cancer therapy, as depletion of S100A4 reprograms the TME to a more anti-tumor environment." (PMID 40078995, 2025). "Intracellular S100A4 facilitates proliferation, epithelial-mesenchymal transition (EMT), enhances the stemness of cancer cells, and promotes tumor metastasis." (PMID 40093000, 2025). "Together with its effects on tumor progression and EMT/CSC phenotypes, the potential for S100A4 to confer chemoresistance highlights its pivotal role in the clinical course of OCCC." (PMID 39857966, 2025). "As shown in the averaged intensity-based heatmap and in line with transcriptomic studies in PDAC, tumor cells were further reclassified into 7 different subtypes, based on the expression of Pan-Ck, Ck-7, CD44, S100A4 and CA-IX." (PMID 39575252, 2024). "Galectin-1 and S100A4 were identified as upregulated proteins in the primary and secondary CT26 tumor tissues, and these were previously reported to contribute to the poor prognosis of CRC patients." (PMID 38612832, 2024). "This study aims to analyze the general and medical characteristics of CRC patients, with a particular focus on the expression patterns of S100A4 and S100A14 proteins and their correlation with tumor location and various clinical parameters." (PMID 39205741, 2024). "Some clusters expressed a combination of markers associated with tumor proliferation and invasiveness, such as CD44, S100A4, CD74 and MMP-9 (Tumor 7, 29.1%, n=8; range 0.7-81.5% per PDAC)." (PMID 39575252, 2024). "This study demonstrates, for the first time, that the tumor cells within LVSI are positive for IL-12R-B2 and S100A4." (PMID 38542414, 2024). "The expression of S100A4 and S100A14 proteins was assessed using immunohistochemistry, and their correlation with clinico-pathological features and tumor location was evaluated using statistical analysis." (PMID 39205741, 2024). "In NEP-mediated metastatic outgrowth, S100a4 neutralization by monoclonal antibody S100a4 or inhibition of S100a4-RAGE interaction by sRAGE, a soluble decoy receptor, substantially diminished the tumor cell growth in a co-culture of Padi4KO cells with NEPs." (PMID 36973439, 2023). "As expected, we observed tumor mesenchyme highly positive for SMA, followed by positivity for S100A4 and TE-7." (PMID 36672620, 2023). "In this study, we found that several CAF-related markers, including PDGFR-β, α-SMA, FAP-α, S100A4/FSP1, collagen type I, and Twist1, were expressed at high levels in stromal CAFs in the proximity of tumor areas in BMs." (PMID 36860926, 2023). "Next, another two trajectory branches, EMT-induced XIST+ tumor cells and invasive and migrative FOSB+ tumor cells, were separated after S100A4+ tumor cells." (PMID 37430270, 2023). "A distinct expression pattern of PDGFR-β, S100A4/FSP1, FAP-α, α-SMA, and collagen type I in the stromal CAFs was observed in relation to the tumor area." (PMID 36860926, 2023). "S100a4 has also been shown to play a role in EMT and metastasis and is highly expressed in murine PDAC mesenchymal tumor cells, patient cell lines, and PDAC patients with high-grade tumors, suggesting a clear association with EMT." (PMID 36828915, 2023). "In the tumor array, correlations were observed between S100A8 and S100A4 (R = 0.66), S100A9 (R = 0.62) and S100A10 (R = 0.46)." (PMID 37627239, 2023).
tumor (continued). "In the tumor array, correlations were observed between S100A9 and S100A8 (R = 0.62), S100A4 (R = 0.78), S100A10 (R = 0.51), S100A12 (R = 0.76), and HMGB1 (R = 0.80)." (PMID 37627239, 2023). "In tumor-derived CAFs from both the patients, we observed high expression of SMA mRNA and protein (100% by ICC and 84% by flow) while a low expression of S100A4 mRNA and protein (1% by ICC and 5% by flow)." (PMID 36672620, 2023). "S100A4 can enhance EGFR/ErbB2 receptor signaling pathway to induce cell proliferation and promote tumor progression." (PMID 37873538, 2023). "Within the primary tumor cohort, the subgroup “MACC1 and S100A4 high” experienced the shortest MFS, while the subgroup “MACC1 and S100A4 low” showed the longest MFS (median follow up: 167.2 months; median MFS of 69 and 131 months, respectively; p < 0.0001)." (PMID 36008464, 2022). "Following severe hypoxia, S100A4 is upregulated and interacts with NMIIA; this inhibits NMIIA activity and thus derepresses tumor cell migration." (PMID 35392912, 2022). "It was recently reported that S100A4 enhanced the expression of mouse SAA1 and SAA3, which stimulated expression of RANTES, G-CSF, MMP2, S100A8, and S100A9 to promote tumor metastasis." (PMID 35936690, 2022). "Moreover, S100A4 might induce tumor progression through the stimulation of angiogenesis." (PMID 36499426, 2022). "Firstly, we evaluated the ability of S100A4 and MRC2 as biomarkers by analyzing tumor and healthy prostatic regions with immunohistochemical techniques (n = 11)." (PMID 36613987, 2022). "S100-derived peptide (ELKVLMEKEL) was found to compete for the RAGE site required to bind ligands, such as S100P, S100A4, and HMGB1, and reduced RAGE-mediated NF-κB activation, inflammation, tumor growth, and metastasis in different cancer cells." (PMID 35956875, 2022). "S100A4(+)/HIF-1α(−) tumor cells are subsequently recruited to, and migrate along, preexisting vessels in the presence of extracellular VEGF released by S100A4(+)/HIF-1α(+) GBM cells." (PMID 35392912, 2022). "S100A4 is a member of the S100 CBP family, which is produced by tumor cells as well as stromal cells." (PMID 35317077, 2022). "We have shown that cancer-derived hypoxic S100A4-positive cells accumulate higher levels of 18F-FDG than other normoxic and hypoxic cancer cells from the A431 cell-derived tumor." (PMID 33994540, 2021). "We believe that the increment of glucose demand in tumor cells with EMT, which is accompanied by human S100A4 expression under hypoxia, can be measured as SUVmax in A431 inoculated mouse 18F-FDG-PET." (PMID 33994540, 2021). "S100A4 expression had a great influence on migration and invasion abilities of HCC cells, as well as sphere formation and tumor initiation assays." (PMID 34035222, 2021). "The combination of both S100A4 and DKK1 clearly improves the prognostic value in CRC compared to each tumor marker alone." (PMID 35008201, 2021). "If patients expressed low levels of S100A4 and high levels of DKK1 in the tumor, the five-year survival was 90% (±7.0%) in the first cohort and 91% (±6.1%) in the second cohort." (PMID 35008201, 2021). "Compared with para-cancer tissues, the expression levels of S100A4/S100A6/S100A10/S100A11/S100A13/S100A14/S100P were higher in HCC tissues, while the expression levels of S100A8/S100A9/S100A12 were decreased in tumor tissues." (PMID 33815482, 2021). "S100A4 protein has been shown to bind the cell surface receptor RAGE, mediating tumor cell survival and metastasis." (PMID 33549040, 2021). "Next, we determined the mRNA levels of S100A4 and DKK1 in micro-dissected primary tumor tissues of two independent patient cohorts by gene-specific qRT PCR." (PMID 35008201, 2021). "S100A4 expression is positively related to the tumor-node-metastasis (TNM) staging and tumor size in PC; the larger the tumor size or the higher the TNM stage, the higher S100A4 expression is." (PMID 34527585, 2021).
tumor (continued). "In vivo models showed that the tumor initiation time of S100A4 down-regulated HCC-LM3 and MHCC97-H cells was sharply delayed for 1 to 2 weeks depending on the number of tumor cells implanted, and tumor sizes were also smaller as expected." (PMID 34035222, 2021). "The Ca2+-binding protein S100A4 and its interacting partner, Ca2+-dependent protein crosslinking enzyme tissue transglutaminase (TG2), promote tumor cell migration." (PMID 34282767, 2021). "High S100A4 and low DKK1 expression levels in the primary tumor resulted in a five-year MFS of 29% (±17.1%)." (PMID 35008201, 2021). "Multivariate analysis showed that all of them were independent prognostic indicators for OS, and exosomal S100A4 level, OPN level, tumor size, tumor capsule, and tumor thrombus were independent predictors for TTR." (PMID 34035222, 2021). "We further compared the effects of depletion of S100A4+ TAMs and inhibition of PPAR-γ on tumor growth." (PMID 34145030, 2021). "Moreover, S100A4 is considered a metastasis-promoting factor also because the protein is released by activated stromal cells (e.g., fibroblasts, immune and vascular cells) in the tumor microenvironment, where it fosters growth factors release, angiogenesis and overall tumor survival." (PMID 33918416, 2021). "S100A4 regulates cellular proliferation, migration, invasion, apoptosis, and EMT in various tumor cells." (PMID 33549040, 2021). "Consistently, we found that CD206 expression levels in tumor tissues were also higher in E7710-bearing S100A4WT mice compared with S100A4KO mice, suggesting that S100A4 sufficiency is mandatory for the expression of protumor markers in TAMs." (PMID 34145030, 2021). "While LY2109761 treatment reduced S100A4 EMT marker levels, the phenotypic transformation of cancer cells and the relationship between TGFβ signaling, EMT, and tumor metastasis remain to be examined in depth." (PMID 33391538, 2021). "Silencing of both S100A4 and MTA1 in endothelial cells reduced tumor angiogenesis in vitro in MSS31 mouse endothelial cells and the formation of new blood vessels in vivo in xenografted mice inoculated with PANC-1 human pancreatic carcinoma cells." (PMID 34209679, 2021). "Expression of S100A4, ACKR3, and CDH1 proteins in tumor samples from Doc-resistant and Doc-sensitive PCa patients was detected by western blotting and IHC." (PMID 31895690, 2019). "Recent studies showed that nuclear expression of the cytoskeletal protein S100A4 and the cancer stem cell marker CD133 are practical predictors of tumor progression, as they can be tested in histologic specimens." (PMID 31687154, 2019). "Taken together, these data suggest that S100A4 released by bone metastatic MDA cells plays critical roles in stimulating osteolysis and increasing tumor burden in the bone marrow." (PMID 31667000, 2019). "S100A4, in a reciprocal manner, activates geminin-overexpressing cells to secrete CCL2 that recruits M0-macrophages from the stroma into the tumor." (PMID 31844158, 2019). "In addition, S100A4 may affect the expression and activity of matrix metalloproteinases, accelerate degradation of the basement membrane, and promote neovascularization, which inhibits the adhesion of tumor cells and increases their motility." (PMID 31526392, 2019). "When asking the same question using primary splenic MDSCs from MCA205 tumor-bearing WT or S100A4−/− mice, only cleaved caspase-3 and cleaved caspase-9 were increased in S100A4−/− MDSCs compared with levels in their WT counterparts." (PMID 29556233, 2018). "We also found that the expression of S100A4 was relatively low in LLC cells when compared with A549 cells and tumor sections." (PMID 29449540, 2018). "Comparable to results with S100A4−/− mice, tumors in TLR4−/− mice were significantly smaller than those in WT mice starting at day 17 after tumor-cell inoculation." (PMID 29556233, 2018).
tumor (continued). "Upon co-culture with tumor cells, fibroblasts downregulate the expression of the CAF marker S100a4 compared with their 3D mono-cultured counterparts." (PMID 29435153, 2018). "The results demonstrated that RP11-79H23.3 inhibited tumor angiogenesis, whereas si-RP11-79H23.3 led to a higher CD31 and S100A4 expression and more microvessels compared with the control group." (PMID 30149689, 2018). "S100A4 is known for inducing proliferation, EMT, migration and invasion in vitro and tumor metastasis events in vivo." (PMID 28423501, 2017). "The detection of S100A4 in the primary ESCC tissues was a valuable predictor for poor outcome and tumor cell invasion in primary ESCC." (PMID 29069865, 2017). "S100A4 as Wnt/β-catenin target gene as well as MACC1 were independently found at the tumor invasion front in CRC patients." (PMID 27331819, 2016). "TNM stage and age were also included in the final model, and the variables entered were S100A4, TNM stage, age, gender, tumor localization (colon vs. rectum), and differentiation." (PMID 27273130, 2016). "The upregulations of S100A4, MARCKSL1, BCAM, BAG4, IPO4 and CPSF7 in pHAGE-ELL(C595A) tumours were confirmed." (PMID 27009366, 2016). "We also observed co-localization of CK19 and S100A4 as well as CK19 and vimentin in early tumor lesions." (PMID 27323406, 2016). "Secretion of S100A4 was shown to synergize with VEGF to strongly promote angiogenesis and enable tumor growth." (PMID 27598148, 2016). "Our data show that several S100 genes, i.e. S100A4, S100A6, S100A10, S100A8, and S100A9, are expressed at very high levels in both tumor cells and TAMs." (PMID 27215396, 2016). "A meta-analysis of eight studies analyzing the prognostic value of S100A4 expression on overall and disease-free survival in CRC consolidates the correlation of high S100A4 expression in tumor tissues with low survival rates of the patients." (PMID 27331819, 2016). "Meghnani and colleagues also reported an up‐regulation of the RAGE ligands S100B, S100A2, S100A4, S100A6 and S100A10 in RAGE overexpressing tumours." (PMID 26928771, 2016). "Taken together, these results convincingly confirm that nuclear expression of S100A4 is a strong prognostic factor in CRC, and that the prognostic significance is retained across tumor stage and localization." (PMID 27273130, 2016). "Multivariate analysis suggested that patient age (P=0.035), tumor size (P=0.002), TNM stage (P=0.001) and S100A4 upregulation (P=0.000) were independent prognostic indicators for the disease." (PMID 23760193, 2013). "S100A4 and S100A9 proteins have been described as playing roles in the control of tumor growth and metastasis." (PMID 23667563, 2013). "The results showed that patient age (P=0.035), tumor size (P=0.002), TNM stage (P=0.001) and S100A4 upregulation (P=0.000) were independent prognostic indicators for the disease." (PMID 23760193, 2013). "The differential expression of S100A4 and S100A9 in both healthy animals and in animals with ongoing inflammatory disease or tumor burden was striking." (PMID 23667563, 2013). "Next, we wanted to examine the expression of S100A4, ephrin-A1 and osteopontin in NSCLC tumor tissue." (PMID 22853000, 2012). "Reduced S100A4 and MMP9 expression was confirmed on protein level by immunohistochemistry of tumor tissue from both groups." (PMID 22878175, 2012). "The S100 proteins are almost exclusively present in the tumor extracts, even though some S100 members are expressed at low, or very low levels, for example S100A2, S100A4 and S100A8." (PMID 20815901, 2010).